LCN2 (lipocalin 2)
Diseases named in the same sentence as LCN2 in open-access papers (continued):
Sharing a sentence is not in itself a finding about the gene and the disease.
Cachexia (continued). "In this review, we mainly focus on LCN2's role in appetite regulation and glucose metabolism and also briefly introduce its effects in other pathophysiological conditions, such as nonalcoholic fatty liver disease, sarcopenic obesity, and cancer‐induced cachexia." (PMID 38035773, 2024). "Although the journey to clinically establish the efficacy and safety of LCN2's anorexic effects is still ongoing, an intriguing perspective emerges: could the development of an anti‐LCN2 agent hold the potential to stimulate appetite, particularly in situations like cancer‐induced cachexia?" (PMID 38035773, 2024). "Thus, the antibody-based disruption of LCN2-induced ferroptosis or chemical inhibition of ferroptosis represent potentially promising strategies for treating the tissue wasting and multiple other deleterious aspects of cachexia." (PMID 36973755, 2023). "In addition, we observed aberrantly increased LCN2 (mRNA and protein) levels during cachexia progression in the eWAT, iWAT, and Gast of cachectic mice, as well as stronger LCN2 protein signals (immunofluorescence staining) in the iWAT and Gast of cachectic mice." (PMID 36973755, 2023). "Interestingly, the highest induced gene Lcn2 is known to be an important contributor to cachexia." (PMID 35031523, 2022). "However, it remains unclear if LCN2 or INSL3 influence other CNS mechanisms of cachexia beyond nutrition at this time." (PMID 34439145, 2021). "However, whether the dysregulation of LCN2 produces meaningful changes in energy balance during cancer-associated cachexia is not known." (PMID 33824339, 2021). "Consistent with LCN2’s proposed MC4R-dependent role in cancer-induced anorexia, pharmacologic MC4R antagonism mitigates cachexia-anorexia, while restoration of Lcn2 expression in the bone marrow is sufficient in restoring the anorexia feature of cachexia." (PMID 33824339, 2021). "We end this review with a discussion of three recently identified central mediators of cachexia, including GDF15, LCN2 and INSL3, all peripherally derived molecules that bind to their cognate receptors in the brain to drive cachexia symptoms." (PMID 34439145, 2021). "First, our ELISA data showed that the serum concentration of LCN2 was significantly higher in cachexia model mice than in control mice (i.e., mice without PDX-based induction of cachexia)." (PMID 36973755, 2023). "Despite improvements in skeletal and cardiac tissue mass, deletion of Lcn2 did not alter ubiquitin ligase or autophagy-related transcripts during cachexia." (PMID 33824339, 2021). "Indeed, just the past 2 years of research identified GDF15, Lipocalin 2 (LCN2) and insulin-like 3 peptide (INSL3) as novel peripherally derived factors that activate CNS circuitry to drive cachexia symptoms." (PMID 34439145, 2021). "Interestingly, a negative correlation between PD-1 mRNA expression and LCN2 mRNA expression in hypothalamic microglia was likely to be observed under the progression of cachexia." (PMID 38685046, 2024). "Collectively, our results from these narrowly focused experimental models revealed that LCN2: (i) induced ferroptosis in adipocytes; (ii) contributed specifically and functionally to the observed wasting of WAT and muscle observed initially in cachexia model mice." (PMID 36973755, 2023). "In the same study, a significant increase in LCN-2 mRNA was found in circulating neutrophils of cachectic mice and it was suggested that together with the bone marrow compartment, neutrophils are the predominant source of circulating LCN-2 during cancer cachexia development." (PMID 37006254, 2023). "Altogether, our LCN2 modulation studies give a precise picture of the role of LCN2 in the MBH and suggest that this protein could serve as a therapeutic target to abolish certain features of cachexia." (PMID 35031523, 2022).
Cachexia (continued). "Moreover, the RNA-seq data indicated that LCN2 affected gene expression in anorexigenic POMC neurons, which may have relevance in cachexia-anorexia, although POMC expression itself was unchanged." (PMID 35031523, 2022). "We did not detect LCN2 in the circulation or CSF of tumor-bearing Lcn2-KO mice, demonstrating that tumor-derived LCN2 does not meaningfully contribute to circulating or central LCN2 levels during cachexia." (PMID 33824339, 2021). "Finally, Lcn2 deletion did not alter acute-phase- and inflammatory-related transcripts in the liver and hypothalamus during the development of cachexia." (PMID 33824339, 2021). "Based on recent literature demonstrating that LCN2 binds to hypothalamic MC4R15 and our observation that feeding behavior improves in Lcn2-KO mice during cachexia, we hypothesized that MC4R antagonism (or inverse agonism) would improve appetite during the development of cancer cachexia." (PMID 33824339, 2021). "Furthermore, a significant increase in the expression of the inflammation-inducing secreted protein lipocalin 2 (LCN2) was similarly observed in hypothalamic microglia at the cachexia stage, but not at the pre-cachexia stage (Unpaired t-test, **p < 0.01 vs. control group)." (PMID 38685046, 2024).
cardiac hypertrophy (14 papers, 2017 to 2023). "Increased expression of Lcn-2 in the heart has been associated with cardiomyocyte apoptosis and the development of pathological cardiac hypertrophy and progression to HF." (PMID 37446174, 2023). "A single-nucleotide polymorphism (SNP), rs13297295, has been found to be associated with elevated levels of LCN-2 and cardiac hypertrophy." (PMID 37155257, 2023). "Published data suggest that glucocorticoid receptors regulate Lcn2 expression in cardiomyocytes, and alterations in its expression are implicated in the progression to pathological cardiac hypertrophy." (PMID 37446174, 2023). "In previous experimental studies, LCN2 deficiency improved the cardiac function by attenuating cardiac hypertrophy in human hypertrophic cardiomyopathy." (PMID 35990970, 2022). "LCN2 drives cardiac hypertrophy and plays a role in maladaptive remodelling of the heart and has been associated with renal injury." (PMID 33603000, 2021). "In some forms of cardiac hypertrophy and acute HF, levels of the neutrophil inflammatory protein known as LCN-2/NGAL were elevated." (PMID 38058391, 2023).
cholangiocarcinoma (14 papers, 2011 to 2025). A carcinoma that arises from the intrahepatic biliary tree (intrahepatic cholangiocarcinoma) or from the junction, or adjacent to the junction, of the right and left hepatic ducts (hilar cholangiocarcinoma). "Silencing of LCN2 represses invasion through a reduction in LCN2/MMP-9 complex formation in cholangiocarcinoma cells, which is linked to reduced survival of patients with cholangiocarcinoma of higher LCN2 expression." (PMID 34202288, 2021). "An increased concentration of LCN2 in cholangiocarcinoma cells was associated with a higher frequency of metastasis in such patients’ groups and a worse prognosis." (PMID 31151292, 2019). "This study investigated the role of lipocalin-2 (LCN2) in human cholangiocarcinoma as a potential therapeutic target and diagnostic marker." (PMID 27782193, 2016). "In cholangiocarcinoma, lipocalin-2 promoted tumor growth, and its expression was negatively associated with patient survival." (PMID 37189804, 2023). "Biliary lipocalin-2 levels of cholangiocarcinoma patients were higher in comparison to those of patients with gallstones, suggesting that lipocalin-2 was excreted by the liver." (PMID 37189804, 2023). "Furthermore, vitamin D/VDR signaling is involved in regulating the expression of lipocalin 2 (LCN2), an oncogene highly expressed in human intrahepatic cholangiocarcinoma tissue." (PMID 35505652, 2022). "Furthermore, increased expression of LCN2 has been reported in the tumor tissues and cell lines of the highly aggressive cholangiocarcinoma." (PMID 32575507, 2020). "A study of cholangiocarcinoma cells observed a decrease in MMP-9 activity, but not in its mRNA levels, after inducing the silencing of LCN2." (PMID 32575507, 2020).
esophageal squamous cell carcinoma (14 papers, 2008 to 2025). Esophageal squamous cell carcinoma (ESCC) is a type of esophageal carcinoma (EC) that can affect any part of the esophagus, but is usually located in the upper or middle third. "The Lcn2 gene promoter of the esophageal squamous cell carcinoma possesses a TPA-response element that interacts with several transcriptional factors to induce Lcn2 transcripts." (PMID 34359830, 2021). "On the other hand, elevated LCN2 has been shown to promote cell differentiation and invasion in esophageal squamous cell carcinoma and depletion of LCN2 suppressed renal tubules apoptosis." (PMID 32272958, 2020). "In esophageal squamous cell carcinoma, LCN2 expression is modulated by the transcription factors TCF7L2 and EGR1, leading to increased activity of matrix metalloproteinase-9 (MMP-9), rearrangement of cytoskeletal F-actin, as well as increased invasiveness and migration through the MEK/ERK pathway." (PMID 34062746, 2021). "For example, lipocalin 2 expression level was found to be significantly higher in oesophageal squamous cell carcinoma (ESCC) than in normal mucosa." (PMID 19077278, 2008). "In esophageal squamous cell carcinoma, EGR1 is the key transcriptional activator of LCN2 within a positive LCN2-MEK/ERK-LCN2 loop to promote the migration and invasion of esophageal squamous cell carcinoma cells." (PMID 35817941, 2022). "Elevated LCN2 expression has also been observed in multiple human cancers including breast, colorectal, pancreatic, ovarian, gastric, thyroid, ovarian, bladder, and kidney cancers, as well as glioma and esophageal squamous cell carcinoma (ESCC)." (PMID 29098164, 2017). "The LCN2/LOXL2/MMP9 ternary complex promoted migration and invasion of oesophageal squamous cell carcinoma (ESCC) cells, as well as tumour growth and malignant progression in vivo, while the iron chelator deferoxamine mesylate (DFOM) inhibited ESCC tumour growth." (PMID 37753805, 2023).
fibrosis (14 papers, 2016 to 2025). the formation of excess fibrous connective tissue in an organ or tissue in a reparative or reactive process. "Because we have previously shown that NGAL is an MR target in extra-intestinal fibrosis, we next quantified both mRNA (Lcn2) and protein NGAL levels in the colon of DSS-treated mice." (PMID 40634309, 2025). "We previously demonstrated that LCN2 promotes hepatic fibrosis in HFD-fed ob/ob mice by activating HSCs via LCN2/MMP9/STAT3-mediated signaling." (PMID 39832399, 2025). "One-way ANOVA showed a significant difference in the plasma levels of LCN2 among the three groups (controls, nAMD with fibrosis, nAMD without fibrosis, p = 0.048), with the highest levels detected in patients with macular fibrosis (192.77 ± 76.37 ng/ml)." (PMID 33292361, 2020).
leukemia (14 papers, 2014 to 2024). A malignant (clonal) hematologic disorder, involving hematopoietic stem cells and characterized by the presence of primitive or atypical myeloid or lymphoid cells in the bone marrow and the blood. "Inverse co-regulation of Lcn2 and Lcn2-R was observed by Green and coworkers who showed in murine leukemia cell models that the oncogene BCR-ABL increases Lcn2 and represses Lcn2-R expression." (PMID 30404645, 2018). "Of the upregulated genes, Syne1, Atxn10 and Dach1 show activation as early as Day 11, while Ngp, Abca13, Adpgk, Mmp8 and Lcn2 were more significantly upregulated in the later stage, D14 neutrophils,which suggests a sequential activation in Camk1d + neutrophils during leukemia progression." (PMID 38730491, 2024). "Therefore, further research is needed to clarify the specific function of LCN2 in different types of leukemia." (PMID 31519186, 2019). "Patients with many hematologic tumors, including AML, have expression of LCN2, which is required for the BCR-ABL-induced mouse leukemia model and is involved in damaging normal hematopoietic cells and inducing tissue invasion by leukemia cells." (PMID 37818101, 2023). "The Lipocalin (NGAL) (LCN2) complex is found in blood tumor cells from patients with ALL, AML and CLL types of leukemia." (PMID 34319051, 2021). "Paradoxically, the analysis of whole-genome expression profiles from patients with leukemia (including AML, ALL and CLL) shows that LCN2 is downregulated at both mRNA and protein levels compared with healthy controls." (PMID 31519186, 2019).
lymph node metastasis (14 papers, 2009 to 2024). "Clinically, LCN2 was positively associated with differentiation, lymph node metastasis, T staging and a poor prognosis in OSCC patients." (PMID 31819048, 2019). "Collectively, these results support the association between LCN2 expression and lymph node metastasis, and suggest that LCN2 is a potential diagnostic marker for cervical cancer." (PMID 26840566, 2016). "An increase in the expression of LCN2 is linked with a negative prognosis, the presence of lymph node metastasis, the grading of tumors, and the estrogen receptor (ER)- negative status." (PMID 39150915, 2024). "The group with lymph node metastasis at initial diagnosis had low expression of both SERPINA3 and LCN2." (PMID 37408474, 2023). "In addition, the SWATH-MS analysis uncovered that some proteins (like lipocalin-2, LCN2, and S100) related to anti-microbial defense and inflammatory response are enriched in the S/SEVs of OSCC patients with lymph node metastasis." (PMID 37304135, 2023). "The expression of LCN2 was related to OSCC lymph node metastasis, differentiation and T stage but not age or sex." (PMID 36899380, 2023). "On the contrary, LCN2 expression was reduced in AD patients with lymph node involvement in comparison with those without lymph node metastasis (P < 0.009), and similar expression level in ADSCC patients irrespective of lymph node involvement." (PMID 26840566, 2016).
melanoma (14 papers, 2011 to 2025). A malignant, usually aggressive tumor composed of atypical, neoplastic melanocytes. "In addition, LCN2 mutation frequencies are the highest in UCEC, Melanoma, NSCLC, BLCA, COAD, and CHOL." (PMID 33425761, 2020). "For example, melanoma cells expressing SNAIL secrete chemokine CCL2, which leads to the secretion of LCN2 (lipocalin 2)." (PMID 35685630, 2022). "LCN2 expression was also reported to be increased in tumor cells cultured under hypoxic conditions and paralleled the levels of HIF-1A in mouse melanoma cells." (PMID 33604288, 2020). "Our data supported that LCN2 mRNA levels increased in HIF-positive regions in tumor tissues, mouse melanoma cells, and various human cancer cells cultured under hypoxic conditions." (PMID 25467539, 2014). "SNAI1+ melanoma cells display enhanced production of TGF-β, thrombospondin-1 (TSP1), CCL2, and lipocalin 2 (LCN2), which may have additional immunosuppressive effects beyond Treg and DC regulation." (PMID 38426087, 2024).
pancreatic ductal adenocarcinoma (14 papers, 2008 to 2023). An infiltrating adenocarcinoma that arises from the epithelial cells of the pancreas. "We hypothesized that lipocalin-2 levels could be associated with neutrophil activation and nutritional status of pancreatic ductal adenocarcinoma (PDAC) patients." (PMID 37006254, 2023). "Downregulation of LCN2 in two pancreatic ductal adenocarcinoma cell lines (BxPC3 and HPAF-II) with high expression significantly reduced attachment, invasion, and tumour growth in vivo." (PMID 23056397, 2012). "These overall results demonstrate that LCN2 plays an important role in the malignant progression of pancreatic ductal carcinoma and is a potential therapeutic target for this disease." (PMID 23056397, 2012). "Similarly, LCN2 improves adhesion of pancreatic ductal adenocarcinoma cells on collagen I and fibronectin substrata." (PMID 35053376, 2022). "Another important point is that LCN2 promotes HIF-1α and vascular endothelial growth factor (VEGF) expression in several pancreatic ductal adenocarcinoma cell lines which contributes to an increase in vascularity." (PMID 30871254, 2019). "In two pancreatic ductal adenocarcinoma cell lines (BxPC3 and HPAF-II), the downregulation of LCN2 significantly reduces attachment, invasion and tumour growth in vivo, but not proliferation or motility." (PMID 25476483, 2015). "Downregulation of LCN2 in two pancreatic ductal adenocarcinoma cell lines (BxPC3 and HPAF-II) with high LCN2 expression significantly reduced attachment, invasion, and tumour growth in vivo, but not proliferation or motility." (PMID 23056397, 2012). "In pancreatic ductal adenocarcinoma (PDAC), depletion of LCN2 could diminish extracellular matrix deposition, immune cell infiltration, and tumor growth." (PMID 33425761, 2020).
ulcerative colitis (14 papers, 2015 to 2025). An inflammatory bowel disease involving the mucosal surface of the large intestine and rectum. "Lcn2 (Neutrophil Gelatinase-associated Lipocalin) is a gene expressed during colonic inflammation and whose translated product (Lipocalin-2) is used as a clinical indicator of ulcerative colitis." (PMID 39337636, 2024). "The identified immune biomarkers (CCL18, DUOX2, GREM1, LCN2, and TNC) demonstrated strong diagnostic efficacy and are key immune genes for ulcerative colitis (UC)." (PMID 40584713, 2025). "LCN2 serves as a dependable indicator of illness severity in ulcerative colitis and CD, differentiating between active disease and remission with heightened sensitivity compared to CRP." (PMID 38926732, 2024). "Fecal lipocalin-2 levels were elevated ~4–5-fold in active ulcerative colitis and active Crohn’s disease compared to patients with inactive disease, the latter still being ~4–5-fold higher compared to stool from healthy controls." (PMID 37189804, 2023). "This is likely due to low number of neutrophil infiltrates in these mice, since LCN2 is a unique marker of neutrophil inflammation in patients with ulcerative colitis." (PMID 32188494, 2020). "Finally, showing promise to distinguish between different inflammatory diseases, fecal lipocalin-2 concentrations were reported to be higher in active ulcerative colitis compared to active Crohn’s disease." (PMID 37189804, 2023). "Furthermore, this protein also marks the severity of intestinal inflammation because the significant up-regulation of Lcn2 also observed in both active ulcerative colitis and active Crohn’s disease." (PMID 26151867, 2015). "The expression levels of core immune genes including CCL18, DUOX2, GREM1, LCN2, and TNC in ulcerative colitis models were detected by fluorescence q-PCR." (PMID 40584713, 2025). "Recent reports have shown systemic up-regulation of LCN2 in IBD murine models and patients with ulcerative colitis, suggesting that LCN2 has potential as a sensitive biomarker for intestinal inflammation." (PMID 35470375, 2022).
acute pancreatitis (13 papers, 2008 to 2025). An acute inflammatory process that leads to necrosis of the pancreatic parenchyma. "We further examined the effects of Lcn2 depletion-mediated iron accumulation on l-arginine-induced acute pancreatitis in mice, a widely used experimental model that can cause pancreatic oxidative injury, sterile inflammation, and extensive necrosis." (PMID 33510144, 2021). "Collectively, these studies suggest that LCN2 exerts a protective effect on acute pancreatitis potentially through the inhibition of ferroptotic response." (PMID 33510144, 2021). "In addition, higher urinary lipocalin-2 levels were related to disease severity and predicted survival of patients with acute pancreatitis." (PMID 37189804, 2023). "This phenotype of Lcn2 depletion-mediated acute pancreatitis could be prevented by treatment with the ferroptosis inhibitor liproxstatin-1 or the iron chelator DFO." (PMID 33510144, 2021). "Recently, elevated serum LCN2 has been identified in acute pancreatitis patients." (PMID 23056397, 2012). "On the other hand, a second cohort of patients with acute pancreatitis did not reveal differences in urinary lipocalin-2 levels compared with the reference group." (PMID 37189804, 2023).